TRAV29DV5 (T cell receptor alpha variable 29/delta variable 5)
Description:
V region of the variable domain of T cell receptor (TR) alpha chain that participates in the antigen recognition. Alpha-beta T cell receptors are antigen specific receptors which are essential to the immune response and are present on the cell surface of T lymphocytes. Recognize peptide-major histocompatibility (MH) (pMH) complexes that are displayed by antigen presenting cells (APC), a prerequisite for efficient T cell adaptive immunity against pathogens. Binding of alpha-beta TR to pMH complex initiates TR-CD3 clustering on the cell surface and intracellular activation of LCK that phosphorylates the ITAM motifs of CD3G, CD3D, CD3E and CD247 enabling the recruitment of ZAP70. In turn ZAP70 phosphorylates LAT, which recruits numerous signaling molecules to form the LAT signalosome. The LAT signalosome propagates signal branching to three major signaling pathways, the calcium, the mitogen-activated protein kinase (MAPK) kinase and the nuclear factor NF-kappa-B (NF-kB) pathways, leading to the mobilization of transcription factors that are critical for gene expression and essential for T cell growth and differentiation. The T cell repertoire is generated in the thymus, by V-(D)-J rearrangement. This repertoire is then shaped by intrathymic selection events to generate a peripheral T cell pool of self-MH restricted, non-autoaggressive T cells. Post-thymic interaction of alpha-beta TR with the pMH complexes shapes TR structural and functional avidity.
Synonyms: TRAV29/DV5; TCRA; TCRAV21S1; hADV29S1
Tractability: Antibody: a drug acting on it is in phase 2 or 3 trials; its Gene Ontology location is reachable by antibodies, with high confidence; UniProt places it where antibodies can reach, with medium confidence; UniProt predicts a signal peptide or a membrane-spanning region.
Gene: T-cell receptor variable (V) gene on chromosome 14 (22,163,238 to 22,163,870, forward strand). Ensembl gene ENSG00000211810.
Subcellular location: Cell membrane
Pathways (Reactome):
Immune System: Co-inhibition by PD-1; Downstream TCR signaling; Generation of second messenger molecules; Immunoregulatory interactions between a Lymphoid and a non-Lymphoid cell; Phosphorylation of CD3 and TCR zeta chains; Translocation of ZAP-70 to Immunological synapse
Gene Ontology:
Molecular function: MHC protein binding; peptide antigen binding
Biological process: immune response
Cellular component: plasma membrane
Homologues: Orthologues: macaque TRAV29DV5 (89% identical), dog TRAV29DV5 (76% identical), rat Trav19 (73% identical), mouse Trav19 (68% identical). Paralogues in human: TRAV23DV6 (59% identical), TRAV12-3 (46% identical), TRAV12-2 (43% identical), TRAV12-1 (34% identical).